GATA3 (GATA binding protein 3)
Diseases named in the same sentence as GATA3 in open-access papers (continued):
Sharing a sentence is not in itself a finding about the gene and the disease.
salivary duct carcinoma (4 papers, 2017 to 2025). An aggressive, high grade adenocarcinoma that arises from the salivary glands. "NR4A3 negativity is useful in differential diagnosis with acinic cell carcinoma, and GATA3 positivity differentiates it from salivary duct carcinoma." (PMID 41440486, 2025). "Further investigation of MGP expression in other tumor types is needed, especially those for which relatively high TRPS1 or GATA3 expression has been reported, such as salivary duct carcinomas and pancreatic adenocarcinoma." (PMID 36284362, 2022). "This tumor showed, in addition, overlap with poorly cohesive salivary duct carcinoma, a possibility further enhanced by reactivity for AR and GATA3, but not p40." (PMID 39387893, 2025).
sarcomatoid carcinoma (4 papers, 2018 to 2025). A malignant epithelial neoplasm characterized by the presence of spindle cells and anaplastic morphologic features. "Furthermore, sarcomatoid carcinomas from sites other than the lung show variable GATA3 positivity." (PMID 39941848, 2025). "GATA3-positive sarcomatoid carcinoma has never been documented in the past." (PMID 30310702, 2018).
sensorineural deafness (4 papers, 2015 to 2025). "AS a candidate gene for hearing loss, TECTB may act downstream of Gata3 in cochlear supporting cells, with altered expression contributing to sensorineural deafness in hypoparathyroidism, sensorineural hearing loss, and renal disease (HDR) syndrome." (PMID 40901670, 2025).
serous carcinoma (4 papers, 2021 to 2024). "In the present study, 11 (16.3%) of ovarian high-grade serous carcinomas, 1 (5.5%) of ovarian clear cell carcinomas, and 11.1% of ovarian and 5.1% of endometrial endometrioid carcinomas showed focal and weak staining for GATA3, and the mean calculated H score was 10.6." (PMID 39118796, 2024).
systemic sclerosis (4 papers, 2015 to 2021). A chronic disorder, possibly autoimmune, marked by excessive production of collagen which results in hardening and thickening of body tissues. "GATA3 has been reported highly expressed in peripheral CD8+ T cell from patients with systemic sclerosis, and functionally related to IL13 induction." (PMID 35095917, 2021). "GATA3 expression levels within CD8+ T-cells seem a proper biomarker of immune dysfunction in patients with systemic sclerosis, a connective tissue disorder involving multiple organs." (PMID 25803478, 2015). "Interestingly, the percentage of GATA3+ CD8+ T-cells was highest in the systemic sclerosis patients that also had interstitial lung disease, characterised by inflammation and fibrosis." (PMID 25803478, 2015). "In addition, transforming growth factor‐β (TGF‐β), a key factor in organ fibrosis, increases interleukin‐13 synthesis by GATA3 in T‐lymphocytes from patients with systemic sclerosis 33 and GATA3 could physically and functional interact with Smad3, a component of TGF‐β signalling pathway." (PMID 27709831, 2017).
T-cell neoplasms (4 papers, 2022 to 2024). "Distinct enhancer landscapes among GATA-3-associated T-cell neoplasms likely explain the divergent GATA-3 target genes we identified across the continuum of immature and mature T-cell neoplasms." (PMID 36329027, 2022). "As most patients afflicted with GATA-3 driven T-cell neoplasms will succumb to their disease within a few years of diagnosis, these findings suggest opportunities to improve outcomes for these patients." (PMID 36329027, 2022). "Rather, GATA-3 transcriptionally reprograms these T-cell neoplasms, and by doing so, functions as a bona fide proto-oncogene." (PMID 36329027, 2022). "The GATA-3 target genes shared across the continuum of T-cell neoplasms are therapeutically relevant, including immunomodulatory drugs (IMiDs) that lead to IKZF3 degradation, and the CCR4 specific monoclonal antibody mogamulizumab." (PMID 36329027, 2022). "Here we show that GATA-3 is a proto-oncogene across the spectrum of T-cell neoplasms, including those derived from T-cell progenitors and their mature progeny, and further define the transcriptional programs that are GATA-3 dependent, which include therapeutically targetable gene products." (PMID 36329027, 2022). "The oncogenic driving capacity of GATA3 originated from the induction of the transcriptional programs that promote cell growth and proliferation; hence, divergent enhancer landscapes were detected among GATA-3-associated T-cell neoplasms with different target genes." (PMID 39768217, 2024). "Among the GATA-3 target genes identified, 26 were shared among immature (T-ALL) and mature (CTCL) T-cell neoplasms." (PMID 36329027, 2022).
upper tract urothelial carcinoma (4 papers, 2017 to 2026). "GATA binding protein 3 (GATA3) and forkhead box A1 (FOXA1) have been individually implicated in the progression of upper tract urothelial carcinoma (UTUC)." (PMID 38425344, 2024). "Nivolumab + cabozantinib reduced the lesion before nephrectomy, which showed predominantly pleomorphic tumor cells that were PAX8 negative and GATA3/p63 positive, mimicking upper tract urothelial carcinoma." (PMID 42317258, 2026). "Tumor samples from 222 patients with upper tract urothelial carcinomas who were treated with radical nephroureterectomy were analyzed for the expression of seven basal/luminal immunohistochemical markers (CK5, EGFR, CD44, CK20, p63, GATA3, FOXA1)." (PMID 28632777, 2017).
anemia (3 papers, 2009 to 2024). A reduction in the number of red blood cells, the amount of hemoglobin, and/or the volume of packed red blood cells. "Gata3 knockout embryos were shown to have growth retardation, along with severe deformities in spinal cord and brain, massive internal haemorrhage, anaemia and defective liver haematopoiesis, i.e. definitive haematopoiesis, suggesting that Gata3 is essential for the development of various systems." (PMID 30463912, 2018).
atherosclerosis (3 papers, 2020 to 2025). A disease characterized by the build-up of fatty material and calcium deposition in the arterial wall resulting in partial or complete occlusion of the arterial lumen. "Interestingly, several of these transcription factors, including RUNX3, STAT1, IRF7, and the Th2 hallmark GATA3, had already been implicated in lesion formation in experimental models of atherosclerosis." (PMID 41039608, 2025).
bladder adenocarcinoma (3 papers, 2014 to 2025). "S100P along with GATA3 and napsin A expression help to distinguish lung-derived bladder adenocarcinoma from primary bladder adenocarcinoma." (PMID 41164170, 2025). "In addition, nuclear GATA3 reactivity might be useful in the differential diagnosis of bladder adenocarcinomas with signet ring morphology." (PMID 29721106, 2018). "Also, GATA3 might be helpful in the differentiation of urachal from primary bladder adenocarcinomas, with data presented almost exclusively derived from our institutional cohort." (PMID 29721106, 2018).
breast adenocarcinoma (3 papers, 2016 to 2025). "Some authors have shown sensitivities as high as 95% for GATA3 in labeling of mammary adenocarcinomas." (PMID 27088025, 2016).
Chagas disease (3 papers, 2016 to 2022). A parasitic infection caused by Trypanosoma cruzi. "Cardiac patients exhibited higher mRNA expression of IFN-γ, TNF-α and lower mRNA expression of IL-10, Foxp3, AHR, and GATA-3 than those with the indeterminate clinical form of Chagas disease." (PMID 27115869, 2016). "In Chagas disease, TBX21 and IFN-γ expression are correlated with the left ventricular dilation, and the ratio between TBX21 and GATA3 expression is significantly higher in CCC than in non-inflammatory cardiomyopathy, which were also confirmed in our data in both control to CCC or DCM comparisons." (PMID 36072583, 2022).
choriocarcinoma (3 papers, 2022 to 2025). An aggressive malignant tumor arising from trophoblastic cells. "Studies reported GATA3 was frequently expressed in trophoblastic tumours such as choriocarcinoma, placental site trophoblastic tumour, epithelioid trophoblastic tumour and hydatidiform mole." (PMID 37298606, 2023). "In addition, as a transcription factor, GATA3 is another immune tumor marker sensitive to choriocarcinoma." (PMID 35710558, 2022).
chronic obstructive pulmonary disease (3 papers, 2019 to 2024). A chronic and progressive lung disorder characterized by the loss of elasticity of the bronchial tree and the air sacs, destruction of the air sacs wall, thickening of the bronchial wall, and mucous accumulation in the bronchial tree. "GATA-3 DNAzyme is being explored in other airway diseases such as chronic obstructive pulmonary disease (COPD), where inhalation of 10 mg SB010 bid for 28 days in COPD patients significantly reduced sputum eosinophilia with a trend to lower IL-5 levels." (PMID 33917396, 2021). "However, in mouse model of chronic obstructive pulmonary disease (COPD), challenge with S. aureus or Haemophilis influenzae lead to loss of GATA-3 expression in ILC2 and a subsequent increase in the expression of IL-12Rβ2, IL-18Rα, and T-bet giving them an ILC1-like phenotype." (PMID 31781103, 2019).
Co-infection (3 papers, 2017 to 2020). "The reduction in GATA-3 expression followed the absent Th2 cytokine production observed in co-infection with T. gondii." (PMID 28791259, 2017).
collecting duct carcinoma (3 papers, 2022 to 2023). "Co-expression of GATA3 and 34βE12 is relatively rare in renal cell tumors and is often seen in tumors of distal nephron or collecting duct origin, such as collecting duct carcinoma and clear cell papillary RCC." (PMID 35936734, 2022).
endometrioid adenocarcinoma (3 papers, 2020 to 2024). An adenocarcinoma characterized by the presence of malignant glandular epithelial cells resembling endometrial cells. "Endometrioid adenocarcinoma is characterized by squamous, mucinous, or ciliated differentiation and presence of precursor lesion (endometrial intraepithelial neoplasia/atypical hyperplasia), and expression of ER and PR but it is negative for GATA-3 immunohistochemically." (PMID 33235131, 2020).
Ewing sarcoma (3 papers, 2024 to 2025). A small round cell tumor that lacks morphologic, immunohistochemical, and electron microscopic evidence of neuroectodermal differentiation. "The expression of GATA3 in this case is atypical but has been documented in some instances of Ewing sarcoma." (PMID 40084340, 2025).
inflammatory skin disease (3 papers, 2017 to 2024). Inflammatory skin disorders covers a broad category that includes many conditions ranging in severity, from mild itching to grave medical health complications These disorders are common in people of all ages and races. "Recently, the expression of GATA3 in keratinocytes was linked to inflammatory skin diseases in humans; IL-4 was found to increase GATA3 levels in the epidermis whereas a reduced GATA3 expression was found in psoriatic lesions and under regenerative conditions." (PMID 28928464, 2017). "The effect of GATA3 expression change on FLG, which encodes the epidermal barrier protein filaggrin, in keratinocytes was pointed out in human inflammatory skin diseases." (PMID 39364404, 2024).
influenza infection (3 papers, 2020 to 2022). "We also found that aged mice treated with D+Q exhibited a higher percentage of GATA3 expressing influenza NP‐specific CD4 T cells." (PMID 34962049, 2022). "In the infected mice, it is possible that the overwhelming Th1 response induced by influenza infection in the mouse lung reduced GATA3 levels below the level of detection as T-bet can directly inhibit GATA3 expression." (PMID 33373420, 2020). "To determine if exposure to TCS might affect the functional capabilities of influenza responding T cells, we analyzed the expression of the canonical Th1 and Th2 transcription factors, T-bet and GATA3, respectively." (PMID 33373420, 2020). "Upon influenza infection of the recipients, GFP+ ILC2s were found to have downregulated GATA3 expression and upregulated IL-12Rβ2 and IL-18Rα, becoming so-called ex-ILC2s that produced IFNγ upon ex vivo stimulation with IL-12 and IL-18." (PMID 36052086, 2022). "In a mouse model of influenza infection (A/FM/1/47: H1N1-adapted mouse strain), Silver and colleagues observed a striking increase in the proportion of lung T-bet+ ILC1s and a corresponding decrease in the frequency of GATA3+ ILC2s." (PMID 36052086, 2022).
kidney cancer (3 papers, 2017 to 2026). Primary or metastatic malignant neoplasm involving the kidney. "In kidney cancer, GATA2, GATA3, GATA5 and GATA6 were mostly downregulated." (PMID 30872657, 2019).
lupus (3 papers, 2021 to 2024). "GATA3 TF expression, IL-4 production, and potent help provided to B cells characterize the TFH type 2 (TFH2) cell subset, which is overrepresented in the context of lupus and associated with disease activity." (PMID 38649353, 2024). "We previously reported increased GATA-3 expression in lupus CD8+ T cells." (PMID 33763079, 2021). "In addition, IL-2 expanded the IL-13-producing lupus CD8+ T cells that also expressed IL-5 and IFN-γ in association with STAT6 phosphorylation and GATA-3 expression, but not with STAT5 phosphorylation." (PMID 33763079, 2021). "Monitoring urinary sediment mRNA levels of T-bet (key transcription factor of type 1 T helper cells), GATA-3 (key transcription factor of type 2 T helper cells), and FOXP3 (key transcription factor of regulatory T cells) could provide early indicators of disease flares in lupus patients." (PMID 39104393, 2024).
Medullary Carcinoma (3 papers, 2020 to 2025). "The negative GATA3 and INSM1 staining in this case excluded parathyroid lesions and medullary thyroid carcinoma." (PMID 41476594, 2025).
mesenchymal tumors (3 papers, 2016 to 2025). "In contrast to GATA2, which primarily acts as an upstream repressor of adipogenesis, GATA3 and GATA4 are dynamically modulated during differentiation and have been implicated in the transcriptional plasticity of mesenchymal tumors." (PMID 41303462, 2025). "GATA3 is classically involved in epithelial differentiation and immune regulation, yet recent studies have highlighted context-dependent roles in mesenchymal tumors." (PMID 41303462, 2025). "Some studies have shown that GATA3 is expressed in many epithelial and mesenchymal tumors." (PMID 34573939, 2021).
Mycosis (3 papers, 2023 to 2025). "To address the potential caveat that fungal infection fails to establish in the absence of type 2 inflammation, we asked whether temporal deletion of GATA3 during on ongoing infection would result in decreased pulmonary burdens." (PMID 40568097, 2025).
nematode infection (3 papers, 2018 to 2025). "Nevertheless, IFN-γ applied during the onset of nematode infection resulted in the strong accumulation of GATA-3+ effector cells in the blood, confirming our earlier finding of overt systemic effector responses in IFN-γ treated BALB/c mice." (PMID 39910093, 2025). "We have previously shown that intestinal nematode infections lead to the differentiation of GATA-3+ Th2 and GATA-3+T-bet+ Th2/1 hybrid cells." (PMID 30349532, 2018).
osteosarcoma (3 papers, 2021 to 2025). A usually aggressive malignant bone-forming mesenchymal neoplasm, predominantly affecting adolescents and young adults. "In the TF-mRNA network, GATA3, which regulates 5 key targets, is an oncogenic factor and has been reported to be lowly expressed in osteosarcoma, inhibiting OS progression and metastasis by regulating slug." (PMID 40831924, 2025).
Pleural effusion (3 papers, 2018 to 2025). The presence of an excessive amount of fluid in the pleural cavity. "We chose to focus on pleural effusion metastases (n = 152), due to the large interpatient variation observed in levels of FOXA1 and GATA3 for this metastatic site." (PMID 29972720, 2018). "In pleural effusion metastases, however, FOXA1 expression is decreased under evolutionary selection pressure of continuous ERα blockade, while GATA3 levels were not affected." (PMID 29972720, 2018).
preeclampsia (3 papers, 2021 to 2026). Preeclampsia is a hypertensive disorder of pregnancy that is characterized by new-onset hypertension with proteinuria presenting after 20 weeks of gestation, and depending on mild or severe forms may initially present with severe headache, visual disturbances, and hyperreflexia. "Given the association between DLX5/GATA3 dysregulation and elevated PSG9 levels, along with PSG9's expression in the first trimester, PSG9 shows potential as a predictive biomarker for preeclampsia." (PMID 41796334, 2026). "Accordingly, women with preeclampsia (PE) have a higher expression of Th1/Th17 factors (T-bet, RORc) and a lower expression of Treg/Th2 factors (FoxP3, GATA-3) than in normal pregnancies." (PMID 41156157, 2025).
renal agenesis (3 papers, 2019 to 2023). Renal agenesis (RA) is a form of renal tract malformation characterized by the complete absence of development of one or both kidneys (unilateral RA or bilateral RA respectively), accompanied by absent ureter(s). "Gata3 deficiency in the mouse results in bilateral renal agenesis accompanied by impaired ND elongation." (PMID 33976190, 2021). "The clinical phenotypes associated with the GATA3 gene were n ephrosis and renal agenesis." (PMID 37324026, 2023).
Renal anomaly (3 papers, 2008 to 2021). "In humans, loss of the haploid GATA3 allele predisposes patients to an inherited disease manifesting as renal anomaly that ranges widely from vesicoureteral reflux and renal hypoplasia to complete agenesis (i.e., HDR syndrome)." (PMID 33803938, 2021).
sarcoidosis (3 papers, 2020 to 2025). Sarcoidosis is a multisystemic disorder of unknown cause characterized by the formation of immune granulomas in involved organs. "A potential TH2 cell marker yet to be studied in relation to sarcoidosis outcomes is GATA-binding protein-3 (GATA-3), the key transcription factor for TH2 cell differentiation." (PMID 33036432, 2020). "Additionally, CD4+ T cells from sarcoidosis patients exhibited increased PRDM1 and GATA3 expression, while naive markers SELL, TCF7 and LEF1 were reduced in sarcoidosis and active TU compared with healthy donors." (PMID 40469525, 2025).
small cell lung carcinoma (3 papers, 2021 to 2023). Small cell lung cancer (SCLC) is a highly aggressive malignant neoplasm, accounting for 10-15% of lung cancer cases, characterized byrapid growth, and early metastasis. "Finally, we show that SMAD3, ZNF217, KLF13, GATA2, GATA3, KLF7, and PHOX2B are components of CRCs in other cancers, including DLBCL, pancreatic, gastric, breast, and small cell lung cancer." (PMID 35201514, 2021).
urothelial neoplasm (3 papers, 2023 to 2025). A neoplasm involving a urothelium. "In summary, GATA3 amplification is a common event which parallels tumor cell dedifferentiation in urothelial neoplasms, especially in non-invasive pTa tumors." (PMID 39979991, 2025). "This emphasizes the utility of mammaglobin-A in combination with GATA3, a marker that primarily recognizes breast and urothelial neoplasms." (PMID 36980510, 2023).